MTOR (mechanistic target of rapamycin kinase)
Diseases named in the same sentence as MTOR in open-access papers (continued):
Sharing a sentence is not in itself a finding about the gene and the disease.
gastric cancer (continued). "The results indicated that suppression of Akt/mTOR pathway may mediate reduced cell viability by PB2 in gastric cancer cells." (PMID 33627124, 2021). "Moreover, it has not reported the effect of Sodium Oxamate in CRC cells, but, in nasopharyngeal carcinoma, Ox induced cell cycle arrest and apoptosis by inhibition of LDH-A, promoting autophagy in gastric cancer cells to modify Akt-mTOR pathway." (PMID 34123772, 2021). "A high level of mTOR has been observed in breast cancer, glioblastoma and gastric cancer." (PMID 34356619, 2021). "PI3K/Akt/mTOR pathway is involved in the progression of gastric cancer." (PMID 33628319, 2021). "For further confirm whether the Akt/mTOR pathway participates in SS-triggered apoptosis and autophagy in gastric cancer cells, we treated cells with SS and MK-2206 (an Akt inhibitor)." (PMID 33708631, 2021). "Moreover, CCL21-mediated activation of the MALAT1/SRSF1/mTOR axis underpins the development of gastric carcinoma." (PMID 34421979, 2021). "However, our study indeed suggested that TIPRL functioned as a metastasis suppressor in gastric cancer through regulating AMPK/mTOR signaling." (PMID 32719745, 2020). "PI3K/Akt/mTOR pathway is involved in the initiation and progression of gastric cancer." (PMID 32515470, 2020). "LMO3 could promote gastric cancer cell invasion and proliferation through Akt-mTOR and Akt-GSK3β signaling pathways." (PMID 32195177, 2020). "Tapia and colleagues investigated the activation of PI3K/AKT/mTOR signals in gastric cancer (GC), with the overexpression of most important target proteins of the pathway, such as PI3K, AKT, p-AKT, p-mTOR, p-4E-BP1, P70S6K1, p-P70S6K1, eIF-4E, and p-eIF-4E proteins in tumor tissue." (PMID 33066449, 2020). "Besides, miR-495-3p was found to regulate autophagy and, consequently, MDR by its interaction with the GRP78/mTOR axis in gastric cancer." (PMID 33194736, 2020). "Here, we present novel results suggesting that 2,6-DMBQ, a major compound in FWGE, is a novel mTOR inhibitor that exhibits anticancer properties in vitro and in vivo which make it a potential candidate that may be useful in treating gastric cancer." (PMID 32517736, 2020). "Moreover, the combination of 5-FU and temsirolimus, an mTOR inhibitor, reduced the chemo-resistance related persister cells in gastric cancer." (PMID 33330109, 2020). "In addition, miR-196b-5p was reported to increase expression of PI3K/AKT/mTOR protein in gastric cancer cells." (PMID 32308564, 2020). "Our findings were further experimentally validated where AZD5363 demonstrated potent cytotoxic activities in PIK3CA-E542K-mutant gastric cancer cell-lines, subsequently downregulating PI3K pathway encoding molecules, including phosphorylation of mTOR, S6K, and 4E-BP1." (PMID 32070411, 2020). "Here, we investigated the biological function of METTL3/m6A in regulating ncRNA and defined a novel pathway for m6A-dependent primary microRNA (miRNA) maturation and AKT/mTOR activation in gastric cancer, which could be counteracted by everolimus." (PMID 33037176, 2020). "Of note, it has been indicated that the ADAMTS9 might execute its suppressive function in gastric cancer by repressing AKT/mTOR pathway." (PMID 33063817, 2020). "Together, our findings suggest that TIPRL may induce phosphorylation/activation of AMPK, which in turn attenuates the mTOR pathway, leading to inactivation of mTOR signaling and subsequent suppression of cell migration/invasion in gastric cancer." (PMID 32719745, 2020). "2,6-DMBQ is an mTOR inhibitor that can be useful for treating gastric cancer." (PMID 32517736, 2020). "While numerous mechanisms of tumor inhibition are still unknown, there are various small molecule inhibitors which target PI3K/Akt/mTOR pathway have been explored in clinical trials of gastric carcinoma." (PMID 32109290, 2020).
gastric cancer (continued). "Indeed, autophagy activation by mTOR inhibitor rapamycin in chemoresistant gastric cancer cells restored drug sensitivity, which was impaired by overexpressing exogenous ARHGAP5-AS1." (PMID 31097692, 2019). "MACC1 regulates gastric cancer tumor immunity via the c‐Met/AKT/mTOR pathway." (PMID 31557409, 2019). "CircNRIP1 activates AKT1/mTOR pathway by sponging miR-149-5p in gastric cancer." (PMID 31438963, 2019). "In addition, VE not only exhibits potent anti-proliferative effects on human tumour cells but also triggers an autophagic process in human gastric cancer SGC-7901 cells via Akt/AMPK/mTOR signaling." (PMID 30585174, 2018). "In addition, it has also been shown to regulate the phosphorylation of one of the most hampered gastric cancer pathway, that is, protein kinase B/mammalian target of rapamycin (Akt/mTOR) channel and resulted in cell death." (PMID 30274346, 2018). "Similarly, miR-451a was shown to be tumor suppressive in gastric cancer by affecting the PI3K/mTOR pathway." (PMID 29720118, 2018). "In conclusion, PEC treatment might have anti-cancer effect by down-regulation of PI3K/AKT/mTOR pathway leading to G2/M phase cell cycle arrest, autophagic and apoptotic cell death in human gastric cancer cells." (PMID 30096805, 2018). "Based on these results, we speculated that DIRAS3 overexpression inhibits the malignant behavior of gastric cancer cells possibly by reducing the activity of the p-AKT/mTOR pathway." (PMID 30043279, 2018). "Both mTOR and Skp2 play critical roles in gastric cancer (GC) tumorigenesis." (PMID 28446188, 2017). "Meanwhile, cultured cell experiments revealed that mTOR signaling could be one of the major enriched pathways in gastric cancer cells with TRIM44 overexpression." (PMID 28885545, 2017). "Interestingly, the expression of DDX5 and p-mTOR in gastric cancer tissues demonstrated a positive correlation." (PMID 28216662, 2017). "Furthermore, previous studies demonstrated that the mTOR rs2295080 TT genotypes carriers showed a much higher mRNA levels of mTOR transcription by increasing the transcriptional activity of mTOR gene in human gastric cancer cell line SGC-79016." (PMID 29259266, 2017). "To investigate whether mTOR signaling regulate Skp2 expression in gastric cancer, we detected the expression of mTOR and Skp2 in cell lines." (PMID 28446188, 2017). "Mechanically, DDX5 induced gastric cancer cell growth by activating mTOR/S6K1." (PMID 28216662, 2017). "The authors speculated that the observed mTOR independent MMP-7 expression was attributable to the complex regulation of mucosal inflammation in the tissue microenvironment in gastric cancer." (PMID 28634370, 2017). "We also characterized the effects of UCA1 on the PI3K-Akt-mTOR signaling pathway in gastric cancer." (PMID 29212166, 2017). "Therefore, we investigated the possible role of mTOR signaling in DDX5 mediated gastric cancer cell growth." (PMID 28216662, 2017). "Given the early and sustained induction of pS6 in GLI2A-expressing gastric cancers, we tested the function of mTOR signaling in tumorigenesis by treating mice with the mTOR inhibitor rapamycin, which resulted in a strong inhibition of tumor growth in iLgr5;GLI2A mice." (PMID 26859571, 2016). "In addition, it is reported that blocking the CXCR4/mTOR signalling pathway induces the anti-metastatic properties and autophagic cell death in peritoneal disseminated gastric cancer cells." (PMID 27517626, 2016). "Everolimus, an orally administered mTOR inhibitor, showed enhanced 5-FU-induced apoptosis in gastric cancer cells with HER-2 amplification and promising activity in preclinical and early clinical trials: such results, however, have not been confirmed in the phase III GRANITE-1 trial." (PMID 27542243, 2016). "As previously shown, ANRIL could control gastric cancer cell proliferation by regulating the mTOR pathway." (PMID 27557514, 2016).
gastric cancer (continued). "Metformin may also induce apoptosis in human gastric cancer cells via the inhibition of survivin mediated by mTOR through the activation of AMPK or via the inhibition of hypoxia inducible factor 1α and pyruvate kinase M2 signaling pathway." (PMID 27587088, 2016). "It is uncertain whether the combination of HER2-targeted agents and mTOR inhibitors might provide benefit in patients with HER2-positive gastric cancer who became resistant: the identification of predictive biomarkers remains crucial for optimizing efficacy." (PMID 27542243, 2016). "Most of the genetic mutations in gastric carcinoma correlate with changes in biological signals, such as those in the phosphatidylinositol 3-kinase/AKT/mammalian target of the rapamycin pathway (PI3K/AKT/mTOR pathway)." (PMID 26701847, 2016). "Genetic alterations affecting the PI3K/Akt/mTOR pathway are frequently found in gastric cancer." (PMID 25784931, 2015). "To determine whether miR-21 can regulate mTOR signaling pathway in gastric cancer cells, we investigated mTOR and mTORC2 kinase activity in cells transfected miR-21 inhibitor." (PMID 26500453, 2015). "In an additional proof-of-principle approach, we measured the expression of MMP2, MMP7 and MMP9 in MKN45 gastric cancer cells before and after treatment with the mTOR inhibitor rapamycin to investigate the putative link between mTOR signalling and MMP expression in gastric cancer." (PMID 26652716, 2015). "Inhibition of the mTOR pathway suppressed the growth of gastric cancer in vitro and in vivo." (PMID 26500453, 2015). "Thus, also mTOR activation has a role in tumor invasion and metastatic spread and, unsurprisingly, its expression is identified in up to 64 % of gastric cancers." (PMID 26652716, 2015). "Because celastrol inhibited PI3 K/Akt activation in our previous study, we hypothesized that celastrol might interrupt mTOR activity in gastric cancer cells." (PMID 26500453, 2015). "Since BEZ235 alone significantly inhibited the cell proliferation, PI3K/AKT/mTOR signaling pathway may be more crucial for HER2-positive gastric cancer survival." (PMID 26560145, 2015). "We hypothesized that celastrol induces cell cycle arrest of gastric cancer cells by modulating miR-21 expression and mTOR signaling pathway in BGC-823 and MGC-803 cells." (PMID 26500453, 2015). "It has been reported that the mTOR signaling pathway is activated in gastric cancer." (PMID 26500453, 2015). "MMP2, MMP7 and MMP9 have been most extensively investigated in gastric cancer, but never previously in a direct comparison and in association with mTOR expression." (PMID 26652716, 2015). "Moreover, the finding that down-regulation of miR-21 expression can inhibit mTOR activity provides further evidence that inactivation of mTOR is mediated by miR-21 in gastric cancer cells treated with celastrol." (PMID 26500453, 2015). "Based on these results, we speculate that GOLPH3 might be affected progression and metastasis of gastric cancer through the activation of Akt/mTOR signaling pathway." (PMID 25286393, 2014). "In particular, significantly higher GOLPH3 expression was accompanied by high expression of p-mTOR, p-4E-BP1, and p-p70S6 in gastric cancer tissues, and this relationship was significantly associated with the depth of invasion, histological grade, and lymph node and distant metastasis." (PMID 25286393, 2014). "Furthermore, the expression of GOPLH3 is highly correlated with the activation of Akt/mTOR signaling pathway in human gastric cancer samples." (PMID 25286393, 2014). "GOLPH3 combined with Akt/mTOR signaling activation may play an important role in the development, differentiation, invasion and metastasis of gastric cancer." (PMID 25286393, 2014). "Genetic alterations in the PI3K/Akt/mTOR pathway in gastric carcinoma have often been demonstrated." (PMID 25003395, 2014).
gastric cancer (continued). "The significant role of the PI3K/Akt/mTOR pathway in the initiation and development of gastric carcinoma suggests that this pathway may be an appropriate target for cancer therapy." (PMID 25003395, 2014). "Genetic alterations and activities of the PI3K/Akt/mTOR pathway in gastric carcinoma." (PMID 25003395, 2014). "Furthermore, BEZ235 blocked the activated PI3K/mTOR pathway either alone or in combination with nab-paclitaxel in gastric cancer cells." (PMID 24042258, 2013). "It is likely that androgen, instead of estrogen, may increase the mTOR expression; androgen may lead to the high incidence of gastric cancer in men and the strong significance of mTOR rs2295080 in male group in our study." (PMID 23555892, 2013). "Consequently, we detected the mTOR mRNA levels with different genotypes in tissues of gastric cancer patients." (PMID 23555892, 2013). "This raises the questions of how many gastric cancer patients really harbor inappropriate mTOR activation and of whether the administration of everolimus to unselected patient populations is meaningful." (PMID 23930209, 2013). "As a therapeutic target in other cancers, mTOR could also emerged as a potential target for treatment of gastric cancer, spontaneously." (PMID 23555892, 2013). "In this study, we identified whether BEZ235 can down-regulate activation of Akt and mTOR in gastric cancer in vivo or in vitro." (PMID 24042258, 2013). "The present study confirmed that in the gastric cancer AGS cell line, EGF caused Tyr1173 phosphorylation of EGFR and the consequent activation of the key components of the PI3K/Akt-mediated pathway, including PI3K, Akt, mTOR and NF-κB." (PMID 24273605, 2013). "They indicated mTOR is frequently activated in human gastric cancer." (PMID 20929525, 2010). "have also observed mTOR activation in human gastric cancer in vitro and in vivo." (PMID 20929525, 2010). "Moreover, we showed for the first time that RAD001 as a new mTOR inhibitor dose-dependently induced apoptosis in gastric cancer cells by Annexin V assays." (PMID 20929525, 2010). "Localisation of p-mTOR may play an important role in tumour progression and outcomes in patients with gastric cancer." (PMID 19223902, 2009). "Localisation of p-mTOR might thus be critical to tumour progression and outcomes in patients with gastric cancer." (PMID 19223902, 2009). "Interestingly, the cytoplasmic expression of p-mTOR positively correlated with factors related to tumour progression and poor outcomes in gastric cancer, whereas the nuclear expression of p-mTOR negatively correlated with such factors." (PMID 19223902, 2009). "These restored pathways consisted of efferocytosis, neuroactive ligand–receptor interaction, intestinal immune network for IgA production, small cell lung cancer, the mTOR signaling pathway, Th17 cell differentiation, and gastric cancer, which may be directly related to immunity and inflammation." (PMID 40567375, 2025). "HDW can act on the VEGF signaling pathway and PI3K/AKT/mTOR signaling pathway through synergistic regulation of cell apoptosis, participation in angiogenesis and cell differentiation and proliferation, and, thus, further play a therapeutic role in gastric cancer." (PMID 39086391, 2024). "Intriguingly, although mTOR/eIF4E pathway was a pivotal driver for EBV‐positive gastric cancer, it also promoted the production of a substantial subset of abnormal W>F peptides, which exposed the fatal drawback of gastric cancer, increasing their susceptibility to the immune system." (PMID 38994917, 2024). "Knockdown of Sema6D can down-regulate ERK, PI3K/AKT/mTOR signaling pathway-related protein expression and inhibit the proliferation, migration and invasion of gastric cancer cells, which is expected to be an effective target for gastric cancer drug development and has clinical research value." (PMID 40777970, 2024). "Furthermore, LDHA is required for the activation of mTOR in gastric cancer." (PMID 39394200, 2024).
gastric cancer (continued). "By acting as a miR‐149‐5p sponge, circNRIP1 enhances the progression of gastric cancer (GC) via the AKT1/mTOR pathway." (PMID 39239069, 2024). "The PI3K-Akt-mTOR (PAM) pathway is implicated in tumor progression in many tumor types, including metastatic gastric cancer (GC)." (PMID 37749105, 2023). "ILF3 overexpression could control gastric cancer progression via PI3K/AKT/mTOR pathway." (PMID 37337223, 2023). "In addition, we speculated that differentially expressed miRNAs in the exosomal content were taken up by the receptor cells, which might affect the activity of PI3K/Akt/mTOR pathway, and then induce autophagy in gastric cancer cells with TOB1 gene knockout." (PMID 35465266, 2022). "Therefore, we further explored the effect of PSMC2/RPS15A/mTOR pathway on gastric cancer." (PMID 35256584, 2022). "Therefore, the inhibition of PI3K/AKT/mTOR signaling may be therapeutically important in treating gastric cancer." (PMID 36014933, 2022). "Moreover, circular RNA could act as a microRNA-149-5p sponge to promote gastric cancer progression via the AKT1/mTOR pathway." (PMID 35200397, 2022). "Gastric CAFs derived SPOCK1 was significantly associated with tumor differentiation and suppressing SPOCK1 expression in gastric CAFs facilitated the phenotypic alteration of gastric cancer cells towards CSC-like cells where AKT/mTOR and MEK/ERK pathways might participate." (PMID 35360859, 2022). "Everolimus (RAD001) is a mTOR inhibitor and is widely used for the treatment of gastric cancer (GC)." (PMID 35209807, 2022). "Besides, IPA results showed an interaction between PSMC2 and RPS15A/mTOR pathway, suggesting that PSMC2 might be involved in the progression of gastric cancer through RPS15A/mTOR pathway." (PMID 35256584, 2022). "Especially, previous studies found that FA2H (Fatty acid 2-hydroxylase) depletion could lead to decreased chemosensitivity to cisplatin via inhibition of AMPK and activation of mTOR/S6K1/Gli1 pathway in gastric cancer, and turn different cancer cells resistant to PM02734." (PMID 36003143, 2022). "The possible mechanisms of the components of the Zhishi-Baizhu herb pair in treating gastric cancer might be related to luteolin and naringenin, which intervened with the targets AKT1, MMP9, IL-6, CCND1, BCL2, MTOR, and MDM2, and are linked with the PI3K-Akt and IL-17 signaling pathways." (PMID 34899944, 2021). "Therefore, PB2 might promote the apoptosis and autophagy of gastric cancer cells though could inhibition of PI3K-Akt-mTOR signaling pathway." (PMID 33627124, 2021). "Therefore, in this study, we confirmed that SS could simultaneously induce apoptosis and protective autophagy in two gastric cancer cell lines by blocking the Akt/mTOR signaling pathway." (PMID 33708631, 2021). "Furthermore, our study for the first time proved that SS could trigger apoptosis and protective autophagy through blocking Akt/mTOR pathway in gastric cancer cells." (PMID 33708631, 2021). "Therefore, the MET/AKT/mTOR axis may be an important target for Cy to inhibit the growth and migration of gastric cancer cells." (PMID 34830011, 2021). "Importantly, we investigated the therapeutic role of Rg3 in GPL treatment via inhibiting the glycolysis process through PI3K/AKT/mTOR pathway downregulation and miRNA-21 targeting and analyzed the effects of Rg3 to induce cell apoptosis in Atp4a−/− mice treated for gastric cancer cells." (PMID 32076440, 2020). "In addition, the lncRNA-mediated regulation of the mTOR/HIF-1α/P-gp signaling pathway marked by increased HIF-1a mRNA levels in gastric cancer cells might also suggest the alteration of HIF-1α transcriptional activity." (PMID 32014012, 2020). "Therefore, reducing mTOR signaling by an inhibitor could provide antineoplastic effects for treatment of gastric cancer." (PMID 32517736, 2020). "However, a negative association between mTOR rs2295080 and the risk of gastric cancer in Chinese patients was also reported." (PMID 32597485, 2020).